APC (APC regulator of Wnt signaling pathway)
Diseases named in the same sentence as APC in open-access papers (continued):
Sharing a sentence is not in itself a finding about the gene and the disease.
colorectal cancer (continued). "NOTUM inhibition abrogates the ability of APC-mutated cells to expand and form intestinal adenomas, suggesting a potential application for people at a high risk of developing colorectal cancer." (PMID 39065798, 2024). "Mutations in the Adenomatous polyposis coli (APC) tumor suppressor gene are common in colorectal cancer." (PMID 39594797, 2024). "This mouse model harbors an inactivating mutation in the APC gene and thus mimics tumor development similar to colorectal cancer patients with APC mutations (60–70 % of all CRC cases)." (PMID 40276485, 2024). "Mutations that augment Wnt ligand activity, e.g., in the LGR5 ligand RSPO, are mutually exclusive to APC mutations, illustrating two alternative pathways for oncogenic Wnt signaling in colorectal cancer." (PMID 39324706, 2024). "Mutations in the APC gene occur in around 80% of colorectal cancers and trigger the progression of sporadic colorectal cancers." (PMID 38607086, 2024). "APC is a well-known tumor suppressor gene frequently mutated in colorectal cancer, with such mutations typically linked to early tumor development." (PMID 39668832, 2024). "Subsequently, we investigated the impact of depleting ZNRF3 or RNF43 on EGFR clearance at the cell surface in mouse embryonic fibroblasts (MEFs) and human cancer cell lines including APC-mutated colorectal cancer cells." (PMID 38260423, 2024). "Gardner syndrome, an autosomal dominant familial adenomatous polyposis (FAP) subtype caused by APC (adenomatous polyposis coli) gene mutations, leads to numerous adenomas in the colon and potential colorectal cancer." (PMID 38929327, 2024). "For example, most colorectal cancers are caused by mutations in the Adenomatous polyposis coli (APC) gene, which usually acts as a tumor suppressor through β-catenin degradation." (PMID 39766864, 2024). "Patients with FAP are at high risk of developing colorectal cancer due to mutations in the APC gene." (PMID 39867084, 2024). "In a majority of colorectal cancer cases, biallelic mutations of APC—which encodes a key component of the β-catenin destruction complex—lead to unmitigated stabilization of β-catenin, thereby driving constitutive pathway activation independent of Wnt ligands." (PMID 39324706, 2024). "APC is an integral part of the destruction complex that promotes proteasomal degradation of β-catenin; therefore, loss-of-function mutations in APC, which prevent β-catenin degradation, are associated with colorectal cancer." (PMID 38891084, 2024). "The mutation of APC, which occurs in 85 percent of colorectal cancer patients, is also closely related to the stemness of colorectal cancer and Wnt/β-catenin activation." (PMID 38254219, 2024). "Patients with colorectal cancer had large frequency of variants in genes APC (50.2%), KRAS (23.2%), BRAF (14.6%), RNF43 (12.3%), and MSH3 (11.3%)." (PMID 39277826, 2024). "In the case of sporadic colorectal cancers, mutational inactivation of both APC alleles leads to Wnt hyperactivation, and these cells gain the ability to proliferate independently of the intestinal stem cell niche and form neoplastic lesions." (PMID 38247798, 2024). "The inactivating mutation of APC, a vital tumor suppressor in the Wnt signaling pathway, is a key event that occurs early in the majority of colorectal cancer cases." (PMID 38590663, 2024). "Mutations inactivating the APC gene are found in approximately 80% of all human colorectal cancer (CRC)." (PMID 38279052, 2024).
colorectal cancer (continued). "For example, 80% of colorectal cancer (CRC) patients show a mutation in the APC gene, a key protein that has a fundamental role in regulating the Wnt pathway." (PMID 38761292, 2024). "Colorectal cancer exhibits evidence of activation in the Wnt signaling pathway, which is associated with the loss of function of the tumor regulatory factor APC." (PMID 38724565, 2024). "In contrast to colorectal carcinoma, it is unusual to find either APC mutations or microsatellite instability in PMP." (PMID 39435876, 2024). "In an APC-deficient mouse model of colorectal cancer (CRC), rapamycin treatment reduced tumor growth and increased survival of mice." (PMID 37775560, 2023). "All colorectal cancer tumors harbored alterations in the WNT pathway regulator APC; 6 (60%) were KRAS mutated, which were mutually exclusive from BRAF V600E mutations [n = 2 (20%)]." (PMID 36426653, 2023). "Mutations in APC, most of them sporadic, have been found in > 80% of colorectal cancer cases, with many leading to alterations in gut organization including the presence of (precancerous) polyps." (PMID 37128612, 2023). "For instance, truncating mutations in APC are found in approximately 70% of colorectal cancer (CRC) patients, whilst activating mutations in CTNNB1 are far less frequent in this disease." (PMID 37048063, 2023). "This would align with the general understanding of colorectal polyposis in which a second hit to APC is considered a requirement and the first step in the mutational cascade inevitably leading to colorectal cancer." (PMID 37943618, 2023). "Colorectal cancer (CRC) is associated with mutations in APC/Wnt leading to c-myc activation and the overexpression of ODC1, the limiting step in polyamine synthesis." (PMID 36900391, 2023). "APC is a well-known tumor suppressor and most commonly mutated in colorectal cancers, as well as many other types cancers like breast, pancreatic, liver and lung cancer." (PMID 37407577, 2023). "There was a significant association of the APC c.3920T>A; p.Ile1307Lys variant with colorectal cancers, i.e. colon, rectal, and sigmoid cancers, as well as polyposis (p-value = 0.03)." (PMID 37306523, 2023). "Many common alterations associated with advanced colorectal cancer were detected, including loss of function events in APC (OMIM 611731), and hotspot KRAS (OMIM 190070) and BRAF (OMIM 164757) variations (V600E, D595G, and G469A)." (PMID 38051531, 2023). "The rate-limiting event in most sporadic colorectal cancer cases is either loss of APC function or oncogenic beta-catenin mutations." (PMID 36936815, 2023).
colorectal cancer (continued). "Kinetin riboside decreased the intracellular β-catenin levels in colorectal cancer cells with mutations in adenomatous polyposis coli (APC) and β-catenin." (PMID 37463866, 2023). "Somatic APC mutations are present in approximately 75% of the apparently sporadic colorectal cancers." (PMID 37626374, 2023). "Adenomatous polyposis coli (APC) mutation is the hallmark of colorectal cancer (CRC), resulting in constitutive WNT activation." (PMID 36669491, 2023). "Approximately 70% of colorectal cancer cases are initiated by mutations in the tumor suppressor gene APC, which lead to the occurrence of benign adenomas in the intestine, and 15% of adenomas progress to malignant colorectal tumors within 10 years." (PMID 36739270, 2023). "Mutations at specific loci of APC and inactivation of APC can lead to familial adenomatous polyposis, an autosomal dominant pre-malignant disease that usually progresses to colorectal cancer." (PMID 37546388, 2023). "In contrast, previous observations for MGMT promoter hypermethylation in colorectal cancer were that these tumors are more likely to arise from serrated adenomas and serrated adenocarcinomas, which are less frequently APC-mutated." (PMID 37387791, 2023). "APC gene mutations lead to the activation of Wnt pathway in intestinal epithelial cells, and the activated Wnt pathway is of great significance for colorectal cancer cell proliferation and stem cell maintenance." (PMID 36739270, 2023). "A few years later, scientists unraveled the link between mutations in the adenomatous polyposis coli (APC) gene and the progression of hereditary colon cancer, which strongly cemented the close association between Wnt signaling and colorectal cancer." (PMID 37888209, 2023). "The APC tumor suppressor, frequently mutated in colorectal cancer, was also found to interact only with EN2." (PMID 37686522, 2023). "The high frequency of APC gene mutations in colorectal cancers suggests that APC dysfunction and subsequent elevated Wnt activity are early and/or initiating events in colorectal cancer." (PMID 36766749, 2023). "Annotations in ClinVar suggest that intronic mutations in the APC gene observed in these eight DLBCL cell lines have been implicated in familial colorectal cancer." (PMID 36831263, 2023). "drugs that do not develop the resistance caused by the mutation of KRAS and APC should be adopted preferentially in the therapy of colorectal cancer." (PMID 37368936, 2023).
colorectal cancer (continued). "A cross-sectional study evaluated the frequencies of germline mutations in APC in more than six thousand individuals with a history of colorectal cancer in their families." (PMID 37746264, 2023). "Mutations of Wnt pathway components, including β-catenin and APC, lead to constitutive transcriptional activation of Wnt target genes and are tightly associated with many cancers, including the vast majority of colorectal cancers." (PMID 37349336, 2023). "Approximately 80–85% sporadic colorectal cancers carry an APC mutation that results in activated β-catenin signaling and enhanced Wnt target expression." (PMID 37671945, 2023). "Our genomic analysis revealed APC to be among the most commonly mutated genes, which is consistent with the typical molecular profile of colorectal cancer." (PMID 37387791, 2023). "The use of tankyrase inhibitors, which downregulate β-catenin activated by mutations in the APC gene, was reported to be an efficient treatment for colorectal cancer patients." (PMID 36831263, 2023). "In humans, APC is a classical tumor suppressor gene that is mutated in most cases of colorectal carcinomas." (PMID 37489330, 2023). "WNT signaling is known as a major pathway in colorectal cancer and mostly is activated by mutation of the APC gene, which plays an important role in the pathogenesis of colorectal cancer." (PMID 36129915, 2022). "Where patients are suffering with advanced colorectal cancers and carrying APC mutations consideration should be given to dual drug treatments which target Wnt signalling and enhance apoptosis." (PMID 35301819, 2022). "As recovered by our progression model, KRAS mutations in colorectal cancer are known to happen after mutations in APC." (PMID 36469540, 2022). "We deployedthis technology to identify novel genetic regulators of β-cateninnuclear accumulation, a phenotypic hallmark of APC-mutated colorectal cancer." (PMID 36589880, 2022). "For example, the WNT antagonists secreted Frizzled-related proteins (SFRPs) are able to inhibit Wnt/β-cat signalling in colorectal cancer cell lines carrying APC mutations." (PMID 36056393, 2022). "Mutations in the adenomatous polyposis coli (APC) gene are the cause of most familial adenomatous polyposis and colorectal cancer, but are rarely observed in other carcinomas." (PMID 35893795, 2022). "In colorectal cancer, amplifications in cytoband 20q13.33 were associated with early tumoral stages and mutations in APC and KRAS." (PMID 36232418, 2022). "CIN-associated tumors are characterized by mutations in the adenomatous polyposis coli (APC) gene and are considered one of the earliest genetic events in colorectal cancer." (PMID 35912261, 2022). "Adenomatous polyposis coli (APC) mutation is an early event during the initiation of colorectal cancers (CRC)." (PMID 35456978, 2022). "Axin2, as a target gene of the Wnt signaling pathway, was previously categorized as a tumor suppressor gene in a small fraction of colorectal cancers harboring APC gene mutations." (PMID 35875099, 2022). "In adenomatous polyposis coli (APC)-mutated mouse models, depletion of Streptococcus thermophilus plays a key role in colorectal cancer tumorigenesis." (PMID 36033445, 2022). "As a consequence, patients with an APC-related MB should be offered genetic counseling and screened for APC germline mutations with the aim to offer surveillance for colorectal cancer." (PMID 36181537, 2022). "To explore the context‐dependent effects of Wnt signaling, we introduced APC loss‐of‐function mutations in APCWT colorectal cancer cells and performed whole‐genome perturbation screens in these genome‐engineered model systems." (PMID 35904277, 2022).
colorectal cancer (continued). "Mutations in APC have been widely studied in cancer development, with loss of function of the inhibitory gatekeeper APC seen in nearly 80% of colorectal cancers." (PMID 35954407, 2022). "Then, the compounds (S)-1 and (R)-1 were tested in a short panel of colorectal cancer cells with wild-type APC (HTC116) and mutated APC (SW480 and SW620)." (PMID 35267666, 2022). "In this study, we first found that APC mutations mainly occur in colorectal cancer, which is consistent with previous experimental and clinical data." (PMID 35303016, 2022). "Within this scope, we focused on a severe phenotype of colorectal cancer with APC loss and mutated KRAS (adenocarcinoma state)." (PMID 35465155, 2022). "Combinations of Wnt signalling inhibitors with an inhibitor of the Bcl pro‐survival protein family should be considered for the treatment of patients with precancerous colon adenomas or advanced colorectal cancers with APC mutations." (PMID 35301819, 2022). "Inactivating GNAI2 alterations occur in about 6% of colorectal cancer patients, which is about the frequency of oncogenic β-catenin (5%) or conductin (7%) mutations but far below the loss of APC (77%), the major tumor suppressor of the Wnt pathway." (PMID 35115535, 2022). "As the APC gene is one of the most frequently mutated known drivers in colorectal cancer, our study provides potential intervention measures for the associated disease." (PMID 36204371, 2022). "Heterozygous germline mutations of APC predispose to colorectal adenomas and early-age colorectal cancer, which are described by the familial adenomatous polyposis (FAP) syndrome." (PMID 35327645, 2022). "In 536 colorectal cancer samples, the overall mutation rate was about 97.95% (525 out of 536) and the mutant frequency of APC was up to 75%, while the mutation rate of HSF1 was only 1%." (PMID 35006040, 2022). "In the Colorectal Cancer Study, a meta-analysis involving 24 articles and 2025 patients reported that APC gene promoter hypermethylation is an early event in colorectal carcinogenesis and can be used as a diagnostic indicator for early colorectal cancer." (PMID 35141222, 2022). "For instance, familial adenomatous polyposis (FAP) is a precancerous state of colorectal cancer caused by germline mutations in the adenomatous polyposis coli (APC) gene." (PMID 36209184, 2022). "To identify β-catenin nuclear regulatorsin APC-mutated colorectal cancer cells, we testeda panel of colorectalcancer cell lines to identify an ideal cell line for the whole-genomeCRISPR screen." (PMID 36589880, 2022). "The APC gene (Case 2), located at 5q21-22, is also a tumor-suppressor gene, and its inactivation or mutation is associated with colorectal cancer, myeloma, RMS, and adenocarcinoma." (PMID 36686750, 2022). "For this, we used CRISPR/Cas9 in combination with an sgRNA targeting a specific region of the APC gene that frequently harbors protein‐truncating somatic mutations in colorectal cancers." (PMID 35904277, 2022). "APC mutations are frequently found in colorectal cancer and define the onset of the transition from adenoma to carcinoma." (PMID 35014953, 2022). "In FAP, mutation in APC and stabilization of β-catenin results in increased colonic cell proliferation, yielding a presentation of colonic polyps associated with increased colorectal cancer risk." (PMID 35116092, 2022).